FPR2 (formyl peptide receptor 2)
Description:
Pattern recognition G protein-coupled receptor (GPCR) that recognizes peptides with N-terminal formyl methionine, which are derived from invading pathogens or host mitochondria as pathogen or damage-associated molecular patterns (PAMPs and DAMPs). Preferentially recognizes longer peptides or peptides with specific sequences such as the phenol-soluble modulin (PSM) family of formylated peptide toxins produced by Staphylococcus aureus. Ligand binding causes a conformation change that triggers signaling via G(i)/GNAI1 inhibiting adenylate cyclase activity, leading to decreased intracellular cAMP levels. In addition, can recognize a variety of chemically distinct endogenous ligands including proteins and lipids besides formylpeptides and thereby plays multiple roles in inflammation. Acts as a receptor for the chemokine-like protein FAM19A5, mediating FAM19A5-stimulated macrophage chemotaxis and the inhibitory effect on TNFSF11/RANKL-induced osteoclast differentiation (By similarity). Acts also as a ceramide membrane receptor, and long-chain ceramides (C14 to C20) binding induces conformational changes that inhibits diet-induced adipose thermogenesis. Participates in neuroprotection via interaction with humanin/MT-RNR2 and Amyloid-beta protein 42, product of APP. Differential signaling is also defined by receptor oligomerization state. Binding of ANXA1 to FPR2 homodimer elicits activation of p38 MAPKinase pathway leading to HSPB1/HSP27 phosphorylation and IL10 production in monocytes. Whereas agonistic activation of FPR1:FPR2 heterodimers signals a proapoptotic JNK pathway in neutrophils.
Synonyms: ALX; FPRH1; FPRL1; LXA4R; HM63; FPRH2; FMLPX; FPR2A; FMLP-R-II; ALXR
Tractability: Small molecule: a structure with a bound ligand is known; a high-quality ligand is known; it belongs to a druggable protein family. Antibody: UniProt places it where antibodies can reach, with high confidence; its Gene Ontology location is reachable by antibodies, with high confidence; UniProt predicts a signal peptide or a membrane-spanning region. PROTAC: a small molecule that binds it is known.
Target class: Peptide receptor (family A GPCR); N-formyl methionyl peptide receptor; Family A G protein-coupled receptor; Membrane receptor
Chemical probes: BMS-986235 (high quality), ML047
Gene: Protein-coding gene on chromosome 19 (51,752,026 to 51,770,531, forward strand). Ensembl gene ENSG00000171049.
Subcellular location: Cell membrane
Pathways (Reactome):
Signal Transduction: Formyl peptide receptors bind formyl peptides and many other ligands; G alpha (i) signalling events; G alpha (q) signalling events
Immune System: Neutrophil degranulation
Gene Ontology:
Molecular function: amyloid-beta binding; protein binding; scavenger receptor binding; signaling receptor activity; cargo receptor activity; complement receptor activity; G protein-coupled receptor activity; N-formyl peptide receptor activity
Biological process: adenylate cyclase-inhibiting G protein-coupled receptor signaling pathway; calcium-mediated signaling; cell surface receptor signaling pathway; cellular response to amyloid-beta; defense response to bacterium; G protein-coupled receptor signaling pathway; immune response-regulating cell surface receptor signaling pathway; negative regulation of inflammatory response; positive regulation of ERK1 and ERK2 cascade; positive regulation of innate immune response; positive regulation of monocyte chemotaxis; positive regulation of phagocytosis; astrocyte activation; cell adhesion; chemotaxis; complement receptor mediated signaling pathway; inflammatory response; microglial cell activation; phospholipase C-activating G protein-coupled receptor signaling pathway; positive chemotaxis; positive regulation of cytosolic calcium ion concentration; positive regulation of phosphatidylinositol 3-kinase/protein kinase B signal transduction; positive regulation of superoxide anion generation; receptor-mediated endocytosis; signal transduction
Cellular component: cytoplasm; plasma membrane; ficolin-1-rich granule membrane; membrane; specific granule membrane; tertiary granule membrane
Genetic constraint (gnomAD): Loss-of-function variants: 3 observed, 4.22 expected, observed/expected ratio (o/e) 0.71, 90% interval 0.32 to 1.67. That is too few expected variants to judge how well the gene tolerates losing a copy. Missense variants: 372 observed, 456.89 expected, observed/expected ratio (o/e) 0.81, 90% interval 0.75 to 0.89. Synonymous variants: 179 observed, 180.74 expected, observed/expected ratio (o/e) 0.99, 90% interval 0.88 to 1.12.
Homologues: Orthologues: macaque FPR2 (96% identical), dog FPR2 (86% identical), rabbit FPR2 (84% identical), mouse Fpr2 (76% identical), rat Fpr2 (76% identical), mouse Fpr3 (74% identical), rat Fpr2l1 (66% identical), rat Fpr3 (66% identical), mouse Fpr-rs3 (65% identical), rat Fpr2l2 (63% identical), mouse Fpr-rs4 (62% identical), rat Fpr2l2 (59% identical), and 2 more. Paralogues in human: FPR3 (73% identical), FPR1 (69% identical), GPR32 (35% identical), C3AR1 (35% identical), CMKLR1 (34% identical), C5AR1 (31% identical), GPR33 (29% identical), C5AR2 (26% identical).
Diseases named in the same sentence as FPR2 in open-access papers:
FPR2 is named in the same sentence as 204 diseases in open-access papers, as found by Europe PMC text mining. Sharing a sentence is not in itself a finding about the gene and the disease. The quoted sentences say what the papers report.
Alzheimer disease (24 papers, 2009 to 2025). A progressive, neurodegenerative disease characterized by loss of function and death of nerve cells in several areas of the brain leading to loss of cognitive function such as memory and language. "FPR2 is involved in a variety of diseases, including those caused by bacterial infection, inflammation, asthma, Alzheimer’s disease and cancer." (PMID 34976024, 2021). "Formyl peptide receptor 2 is involved in accelerating senescence of hippocampal NSCs by amyloid-β42, a major component of amyloid plaque formation, a representative cause of Alzheimer’s disease (AD)." (PMID 34833124, 2021). "Although many studies show that ALX/FPR2 deficiency increases inflammation, a few studies show that knockout of Alx/Fpr2 may be beneficial for some outcomes, such as in the brain for improving cognition and detrimental effects of Alzheimer disease in mice." (PMID 40972651, 2025). "In the CNS, the activation of FPR2 has been demonstrated to reduce the neuronal damage in Alzheimer’s disease, ischemia or sepsis." (PMID 35328727, 2022). "Compared to the control brain, a higher FPR2/ALX level was also detected in Alzheimer’s disease (AD)." (PMID 35153778, 2022). "Despite the fact that both peptides, by activating FPR2, induce migration and increase the phagocytic activity of monocytes in the brain, they have a different role in the course of Alzheimer's disease." (PMID 34105114, 2021). "It plays an important role in the pathogenesis of Alzheimer’s disease (AD), exerting its pro-inflammatory responses through FPR2." (PMID 23549262, 2013). "The formyl peptide receptor 2 (FPR2) is involved in the pathogenesis of Alzheimer’s disease." (PMID 35365641, 2022). "Indeed, in humans, ALX/FPR2 and ChemR23 levels are higher in the hippocampus of Alzheimer’s disease patients as compared with controls." (PMID 32121189, 2020). "In the CNS, Aβ protein phagocytosis via ALX/FPR2 was investigated in the Alzheimer’s disease model." (PMID 32795323, 2020). "FPR2 (also named lipoxin A4 receptor (LXA4R, ALX) is involved in the development of chronic inflammatory diseases, such as atherosclerosis, Alzheimer’s disease, colitis, and NAFLD/NASH, through the regulation of cell proliferation, inflammatory responses, and chemotaxis." (PMID 36547446, 2022). "Interestingly, in our previous study, we observed that the beneficial impact of the structurally related FPR2 agonist MR-39 was also limited to the suppression of microgliosis but not astrogliosis in an in vivo model of Alzheimer’s disease." (PMID 37947648, 2023). "For example, FPR2/ALX has demonstrated to be a functional receptor for prion protein fragment PrP106-126, as well as the amyloidogenic peptides serum amyloid A and amyloid-β; which play important roles in the neurodegenerative activity of Alzheimer’s disease (AD) and prion diseases." (PMID 31170199, 2019).
Sepsis (22 papers, 2016 to 2025). Sepsis is defined as life-threatening organ dysfunction caused by a dysregulated host response to infection. "In this study, we identify, for the first time to our knowledge, an SNP (rs11666254) located in the promoter of FPR2/ALX that is associated with increased sepsis hypersensitivity in major trauma patients." (PMID 28679406, 2017). "The SNP rs11666254 in the promoter of FPR2/ALX increases sepsis susceptibility in patients following traumatic injury." (PMID 28679406, 2017). "Investigation of single‐nucleotide polymorphisms in the FPR2 gene identified that the rs11666254 polymorphism was associated with decreased FPR2 mRNA and protein expression, molecular changes that are functionally associated with susceptibility to sepsis after traumatic injury." (PMID 32954491, 2020). "The promoter polymorphism rs11666254 downregulates FPR2/ALX expression and increases risk of sepsis." (PMID 40103822, 2025). "The levels of LXA4 and Fpr2 were significantly elevated in mouse lung tissue in the early stage of sepsis." (PMID 36544058, 2023). "Concomitantly, deletion of Fpr2 alleviated sepsis in LPS-treated mice and improved cardiac dysfunction, which was related to inhibition of inflammation." (PMID 35018584, 2022). "Studies have shown that Fpr2 confers protection against sepsis-mediated tissue damage in mice and both Fpr1 and Fpr2 are indispensable for mouse resistance to Listeria infection." (PMID 32038501, 2020). "As seen in whole blood samples from sepsis patients, TLR2 induction correlated with the overexpression of genes associated with immunosuppression (IL10, FPR2) or wound healing (MMP9)." (PMID 31396208, 2019). "The purpose of this study was to investigate the association between genetic variants of the FPR2/ALX gene and sepsis after severe trauma as well as to further analyze the functions of sepsis-related genetic polymorphisms." (PMID 28679406, 2017). "In animals with sepsis, Fpr2/3 gene activation can be induced by TNF-α, and FPR2/ALX activation can decrease TNF-α levels." (PMID 28679406, 2017). "In summary, the association between the common variants of FPR2/ALX and sepsis was evaluated in severe trauma patients." (PMID 28679406, 2017). "FPR2 is also induced in the early phase of sepsis and functions in cerebral inflammation." (PMID 32174955, 2020). "In addition, mouse neutrophils expresses reduced levels of FPR2 (Fpr2) in a sepsis model, thus failing to infiltrate the site of infection." (PMID 32038501, 2020). "The rs11666254 polymorphism, which had statistical significance, was genotyped in an additional 371 patients, and logistic regression analysis was performed to determine associations between the FPR2/ALX gene polymorphism and sepsis susceptibility after severe trauma." (PMID 28679406, 2017). "However, based on the conserved structure of PSMs and the fact that all PSM types have been shown to activate immune cells via recognition by the formyl peptide receptor 2 (FPR2), it is fair to assume that other PSMs may also promote sepsis." (PMID 28596942, 2017). "Additionally, the Fpr2/3 gene (an orthologue to human FPR2/ALX) deficiency in mice impairs bacterial clearance and aggravates the host response in polymicrobial sepsis, which suggests that FPR2/ALX has a pivotal role in the development of sepsis." (PMID 28679406, 2017). "Focus was given to the pro-resolving protein AnxA1 and its cognate receptor FPR2/ALX, a pathway that has been shown to exert a degree of protection in experimental tuberculosis, sepsis, pneumococcal pneumonia, and influenza." (PMID 35293862, 2022). "On the basis of these biological functions, activation of FPR2/ALX has been shown to be essential in models of experimental inflammation, such as sepsis, cerebral inflammation, acute lung injury, and stroke." (PMID 28679406, 2017). "It is therefore a little surprising that animals lacking FPR2 display marked macroscopic effects, such as lethality, in experimental sepsis." (PMID 35797341, 2022).
Sepsis (continued). "Formyl peptide receptor 2-lipoxin receptor (FPR2/ALX) modulates the anti-inflammatory response and therefore may be a target for treating sepsis." (PMID 28679406, 2017). "In a mouse model of E. coli pneumonia, 15-epi-LXA4-ALX/FPR2 interaction selectively upregulated the NF-κB negative regulators A20 and SIGIRR, thereby decreasing NF-κB activity, which may inhibit pulmonary neutrophil infiltration while increasing bacterial clearance and improving sepsis survival." (PMID 40799817, 2025).
colitis (20 papers, 2012 to 2025). Inflammation of the colon. "Our study identified a natural compound, columbamine (COL), that can activate LC3‐associated efferocytosis and attenuate DSS‐induced colitis by biasedly targeting FPR2 on macrophages." (PMID 37994307, 2023). "Fpr2 deficiency increased susceptibility to chemically induced colitis, delayed the repair of damaged colon epithelial cells, and heightened inflammatory responses." (PMID 37322488, 2023). "Fpr2 deficiency led to an increased E. coli population in the colon and delayed recovery of damaged colon epithelial cells in mice with colitis." (PMID 37322488, 2023). "There were similarities in the phenotype among Fam3D−/−, Fpr2−/−, and Fpr1/2−/− mice, and mice deficient in another Fpr2 agonist Cramp in that they all showed increased susceptibility to chemically induced colitis." (PMID 33219235, 2020). "Fpr2 deficiency, resulting in an increase of E. coli in the colon of Fpr2−/− mice with colitis, may be a compensatory response by the host." (PMID 37322488, 2023). "Fpr2 deficiency increased E. coli population in the colon of mice with colitis." (PMID 37322488, 2023). "Collectively, these data indicate that FPR2 is required for COL‐induced attenuation of mouse colitis." (PMID 37994307, 2023). "As expected, deletion of FPR2 abolished the anti‐colitis activity of COL in ameliorating body weight reduction, DAI increase, and colon shrinkage." (PMID 37994307, 2023). "This study provides a novel therapeutic strategy for inflammatory diseases, including colitis, via enhancing FPR2‐mediated efferocytosis." (PMID 37994307, 2023). "CRAMP expression was increased in Fpr2+ colon epithelial cells of the mice with colitis induced by DSS." (PMID 33104252, 2021). "In the DSS-induced colitis model, Fpr2/3 knockout mice showed a more severe disease phenotype and exhibited delayed wound healing due to a decrease in migrating monocytes, which facilitated epithelial remodeling via downregulation of the CCL20-CCR6 axis." (PMID 33082511, 2020). "Also, in Fpr2 deficient mice, colon epithelial cells are defective in response to commensal bacterium-stimulated crypts development, with reduced severity in chemically induced colitis but lapsed recovery of mucosa from chronic damage in association with increased tumorigenesis." (PMID 32038501, 2020). "There was also a more severe colitis in Fpr2 KO mice after bacterial infection with increased bacteria in contact with colon epithelial cells." (PMID 32038501, 2020). "CSA13 treatment significantly inhibited colonic collagen Col1a2 mRNA expression and fibroblast accumulation (αSMA and vimentin) in the mice with TNBS colitis that was reversed by Fpr2 shRNA." (PMID 29180648, 2017). "The authors also revealed that in a colitis-induced model, Fpr2-null mice displayed a higher presence of E. coli in the colon, indicating that commensal E. coli may exhibit pathogenic traits, potentially as a compensatory response by the host." (PMID 40733247, 2025). "Furthermore, Fpr2/3-null mice showed reduced monocyte recruitment to injury sites in the same colitis model, emphasizing their role in colonic mucosal wound repair." (PMID 40733247, 2025). "In the colitis model, FPR2−/− mice did not exhibit obvious body weight reduction, but showed a higher DAI compared to the wild type (WT) mice after DSS treatment, indicating that FPR2 partially regulated the DSS‐induced colitis development, which is consistent with a previous report." (PMID 37994307, 2023). "The results showed that blocking FPR2 prevented COL‐induced amelioration of colitis." (PMID 37994307, 2023). "It has been shown that mice lacking Fpr2 or genes that encode anti-inflammatory Fpr2-binding proteins are more susceptible to DSS-induced colitis." (PMID 31234710, 2019). "AnxA1-based mimetics (e.g., Ac2-26), FPR2/ALX agonists, and targeted nanoparticle formulations have shown anti-inflammatory benefits in experimental colitis." (PMID 41550928, 2025).
colitis (continued). "Genetic ablation of the Fpr2 gene or treatment with an FPR2 antagonist abolishes COL‐induced efferocytosis, anti‐colitis activity and LAP." (PMID 37994307, 2023). "WKYMVm, which is a synthetic peptide agonist of FPR2, also has a protective effect on DSS-induced colitis." (PMID 33082511, 2020). "Expression of two key SAA receptors (Fpr2 and Scarb1) was also elevated in the colon tissue of LysMCre;Arntfl/fl mice, reinforcing a potential role for SAA in colitis." (PMID 30455703, 2018). "They possess anti-inflammatory and pro-resolving actions in colitis, via activating their mutual receptor ALX/formyl peptide receptor 2 (FPR2)." (PMID 26967051, 2016). "To evaluate whether FPR2 is the target of COL for its anti‐colitis effects, we further administered WRW4 to colitis mice." (PMID 37994307, 2023). "The results of bone marrow chimera experiments indicated that the expression of Fpr2/3 in both hematopoietic immune cells and nonhematopoietic cells was essential to protect the intestine in an experimental colitis model." (PMID 33082511, 2020). "Also, mice deficient in AnnexinA1, an anti-inflammatory protein that binds to Fpr2, fail to recover the damaged epithelium following DSS-induced colitis in mice." (PMID 31234710, 2019). "For example, Bento and colleagues reported that the ALX/FPR2 inhibitor Boc-1 abolishes the anti-inflammatory effects of aspirin-triggered resolvin D1 on LPS-stimulated macrophages derived from murine bone marrow, thereby exacerbating murine DSS-induced colitis." (PMID 33945545, 2021). "In addition, the knockout mice for formyl peptide receptor 2/3 (fpr2/3), orthologs of the human LXA4 receptor FRP2, showed a delayed mucosal healing and increased mucosal ulceration in comparison to their wild type counterparts during the course of acute DSS-induced colitis." (PMID 33807591, 2021).